ERBB2 (erb-b2 receptor tyrosine kinase 2)
Diseases named in the same sentence as ERBB2 in open-access papers (continued):
Sharing a sentence is not in itself a finding about the gene and the disease.
cancer (continued). "This further established a regulation of FA turnover following modulation of ErbB2 signalling by Herceptin in alternative ErbB2-positive cancer cells." (PMID 19190626, 2009). "In regard to molecular markers and gene mutations, the luminal subtype included all the ER-positive cancer lines (P<0.001, 2-tailed Fisher's exact test), and all but two of the ERBB2-positive lines (P = 0.002), half of which were also ER-positive." (PMID 19582160, 2009). "The Estrogen Receptor negative (ER-) branch covered three subgroups of tumors: 1) overexpressing ERBB2 (HER2); 2) expressing genes characteristic of breast basal cells (basal-like cancer); and 3) normal-like samples." (PMID 19761577, 2009). "Two mixed carcinomas showed ERBB2 amplification and overexpression in the two histological components." (PMID 19156142, 2009). "ERBB2 amplification was detected in both histological components of two mixed carcinomas, indicating a common clonal origin." (PMID 19156142, 2009). "Other authors reported that diffuse gastric carcinomas account for 5–6.2% of all ERBB2-amplified carcinomas, which is corroborated by our findings." (PMID 19156142, 2009). "In our study we used EGFR and ErbB2 as targets; both are very well characterized in the field of targeted anti cancer therapy." (PMID 18387177, 2008). "The Erk pathway is activated in many types of cancer and can be activated by numerous oncogenic signals, including ErbB2." (PMID 18700973, 2008). "ErbB3, the major EGFR family member that activates the PI3K/Akt pathway, is required for ErbB2-induced cancer cell proliferation, transformation and colony formation in vitro." (PMID 18700973, 2008). "Trastuzumab, most likely due to a multifaceted mechanism is efficacious against cancer that is driven by ERBB2 gene amplification." (PMID 18841159, 2008). "Understanding ErbB3 functions in the normal mammary gland will help to explain its role in cancer etiology and as a modulator of signaling responses to the mammary oncogene ERBB2." (PMID 19019207, 2008). "ErbB2 is an attractive target since it is overexpressed on cancer cells of a number of different histological types and associated with the malignant phenotype." (PMID 17426702, 2007). "Erbicin is a human anti-ErbB2 single-chain antibody fragment with high affinity and selectivity for ErbB2-positive cancer cells." (PMID 17923870, 2007). "Blocking the function of ErbB2 leads to inhibition of proliferation of cancer cells as demonstrated in preclinical and clinical studies." (PMID 17426702, 2007). "These facts indicate that novel immunotherapeutic strategies to fight ErbB2-positive carcinomas are strongly called for." (PMID 17923870, 2007). "There are currently four known ErbB receptors with ErbB1 (also known as EGFR) and ErbB2 (also known as Neu or HER2) being the most likely to be overexpressed in cancers, and, therefore, the most studied." (PMID 16519802, 2006). "Taken together, our results demonstrate that the ErbB2-specific antibody toxin scFv(FRP5)-ETA can be safely administered intravenously at doses up to 12.5 μg/kg per day to treat cancer patients with ErbB2-overexpressing tumors." (PMID 16168106, 2005). "ErbB2 expression in MCF10A cells has recently been used to model the events in cancer progression that lead to the destruction of the normal acinar architecture of glandular epithelium within the mammary gland." (PMID 16371159, 2005). "Vaccination of cancer patients with a single ErbB2-derived CTL epitope together with GM-CSF as an adjuvant was not very effective, leading only to short-lived CTL responses." (PMID 15812545, 2005).
cancer (continued). "In conclusion, our data demonstrate that effective priming of ErbB2-specific CD8+ T cells occurred upon in vivo application of cancer vaccines consisting of an ErbB2-derived Tc-epitope attached to a liposomal carrier via an adjuvant Pam3CSS lipopeptide anchor." (PMID 15812545, 2005). "Recognizing the alterations in EGFR family tyrosine kinase function galvanized the development of one of the first approved targeted cancer therapeutics, Herceptin, an antibody inhibitor of ErbB2." (PMID 16371159, 2005). "The erbB family of receptors, namely EGFR and ErbB2, are important drug targets for cancer therapeutics and are the focus of a large number of current clinical trials." (PMID 15305194, 2004). "In this regard, we recently reported that RC-3095 and RC-3940-II can inhibit the growth of MDA-MB-435 cancer by downregulating mainly ErbB-2/HER-2, as well as by decreasing the expression of c-jun and c-fos oncogenes." (PMID 14710236, 2004). "Together, we have identified changes that are likely to drive proliferation and anchorage-independent growth of ErbB-2- overexpressing cancer cells." (PMID 14710226, 2004). "ERBB2 overexpression has also been reported in cancers of colon, prostate, ovary and pancreatic origin." (PMID 12942124, 2003). "ERBB2, a known cancer driver which could hijacks MYC’s enhancers by forming a MYC-ERBB2 chimeric ecDNA to elevate the expression level, was also identified." (PMID 40478912, 2025). "Survival analysis using KM plots was conducted for the ERBB2 gene in both cancers." (PMID 40177517, 2025). "Among the ErbB family, the ErbB2/HER2 receptor is a key driver of cancer growth." (PMID 41161384, 2025). "Moreover, several genes, including PTK2, CCND1, and ERBB2, were identified as being closely related to the occurrence and progression of cancer, with their expression levels significantly correlating with patient prognosis." (PMID 40567661, 2025). "While ErbB2 inhibitors such as lapatinib and neratinib are approved and well characterized for cancer therapy, their blood–brain barrier permeability and neuronal specificity remain limited, raising concerns about off-target effects on glial and neuronal viability." (PMID 41226692, 2025). "When ERBB2 (HER2) is amplified or mutated, it becomes activated in a ligand-independent manner, driving activation of downstream pathways controlling the migration, proliferation, survival, and differentiation of cancer cells." (PMID 40178042, 2025). "In addition, it is known that cancer cells alter ganglioside composition to favour receptor dimerisation and signalling as demonstrated for Her2 (ErbB2) and EGFR." (PMID 40941028, 2025). "Furthermore, we observed a similar regulatory role of ESRP1 in i14e generation in both SKBR3 and MKN1 cell lines which has been shown to generate ERBB2 i14e, suggesting a broader conservation of this regulatory mechanism across different cancer types." (PMID 39948369, 2025). "Notably, the immune system-related CD68 and CD86, as well as the cancer-related ERBB2, have a relevance score of 0.8." (PMID 40593564, 2025). "Additionally, 8 upstream regulatory proteins were predicted to be activated, including Rab-like protein 6 (RABL6), heat shock factor 1 (HSF1), epidermal growth factor (EGF), and ERBB2, all of which are involved in the progression of various cancers." (PMID 40301999, 2025). "Trastuzumab is the most therapeutically applied antibody for ERBB2-positive cancers." (PMID 39948369, 2025). "Furthermore, it showed that only patients with FAT1 variants had CRC, and most patients harboured variants in genes such as CHEK2, ERBB2, and KIT in most of the cancers." (PMID 40627234, 2025). "Notably, ERBB2 (also known as HER2) receptor is a proto-oncogene frequently amplified and overexpressed in many human cancers." (PMID 41011267, 2025).
cancer (continued). "Antisense oligonucleotides targeting the 5’ splicing sites of ERBB2 i14e can sensitize trastuzumab therapy, suggesting that combined treatment of ERBB2 i14e ASOs with trastuzumab or trastuzumab-drug conjugates holds great promising benefit for cancer patients expressing ERBB2 i14e." (PMID 39948369, 2025). "ErbB2 expression appears to drive aggressive features in luminal B cancers." (PMID 40689167, 2025). "A human epidermal growth factor erbB-2, also known as Her-2, triggers cell invasive ability, and a high level of Her-2 could promote cancer cell growth, invasive ability, and resistance to chemotherapy drugs in ER-positive cells." (PMID 37957856, 2024). "Moreover, the EGFR/ErbB2 dimer is involved in steps that are crucial for cancer progression, such as cell proliferation, migration and invasiveness." (PMID 38370412, 2024). "Additionally, various small molecule inhibitors targeting EGFR and/or ERBB2 have been approved for treatment of cancers such as NSCLC." (PMID 38713378, 2024). "The activated ErbB2 (also known as neu or HER2) is a major driver of cancer." (PMID 38459595, 2024). "Nrdp1-mediated ErbB3 degradation inhibited cellular proliferation and motility, while Nrdp1 depletion in BC could accelerate cancer growth by enhancing ErbB2/ErbB3 signaling." (PMID 38835349, 2024). "Furthermore, imputed expression of ERBB2 showed an increase in the cancer region matching previous literature." (PMID 39402626, 2024). "In this study, we took an additional step to evaluate and validate the analytical performance of both NGS panels in detecting gene amplifications, with a specific focus on ERBB2 amplification across various cancer types due to its clinical relevance in the context of targeted therapies." (PMID 39682116, 2024). "This suggests that therapies targeting ERBB2 could be effective for a variety of cancers, offering potential for more effective treatment options across different oncological conditions." (PMID 39684551, 2024). "Consequently, these metabolic adaptations allow the cancer cells to evade the inhibitory effects of ErbB2-targeted therapies, which include suppression of glucose metabolism and energetic stress." (PMID 39097623, 2024). "Moreover, changes in the cancer methylome are coupled with somatic mutations in cancer driver genes, such as CTNNB1, ERBB2, KRAS, and PIK3CA, which consistently recapitulate the somatic evolutionary process and consequential clonality of cancers." (PMID 38566132, 2024). "At the genetic level, HER2 is encoded by the ERBB2 gene (v-erb-b2 avian erythroblastic leukemia viral oncogene homolog 2), which is frequently mutated or amplified in cancers, thus spurring extensive research into HER2 modulation and inhibition as viable anti-cancer strategies." (PMID 39123362, 2024). "Our findings substantially increase biological insights into ERBB2-driven cancers, which may provide new strategies and define new targets for improving outcomes of ERBB2-targeted therapies." (PMID 39067134, 2024). "Moreover, liposomes functionalized with anti-ErbB-2 antibodies can specifically target ErbB-2 positive cancer cells, thereby enhancing the delivery and efficacy of peptide vaccines." (PMID 39204073, 2024). "Of note, IGF1R and ERBB2 drug combinations are already being investigated in the context of cancer." (PMID 38585651, 2024). "ERBB2/HER2 is normally expressed in several cell and tissue types excluding those of hematopoietic origin, and, importantly, is frequently overexpressed in a number of human cancers." (PMID 38638322, 2024). "RAC2 also showed upregulation of proliferative pathways, including signalling by NTRK2/TRKB, characterised by overexpression of the PIK3CA gene, and signalling by ERBB2 in cancer, as reflected by elevated serum concentrations of SHC1, ERBB4, EGFR and ERBB2, compared with RAC3." (PMID 39401856, 2024). "In veterinary medicine, EGFR and ERBB2 have been reported in dogs and cats with cancer." (PMID 39126006, 2024).
cancer (continued). "The ErbB2 gene was selected in this preliminary study as it is involved in inflammation and cancer." (PMID 38533139, 2024). "Our annotation of the pathway ‘Signaling by ERBB2 in Cancer’ (R-HSA-1227990), for example, illustrates the range of mechanisms by which normal ERBB2 signaling is disrupted and the types of small-molecule drugs that target these ERBB2 variants." (PMID 37941124, 2024). "Next, to investigate the gene dosage effect for other cancer-related genes (genes included on the UCSF500 panel other than ERBB2) on HER2 expression, we evaluated a logistic regression model to predict HER2 IHC 3+ (vs IHC 0/1+/2+) status while adjusting ERBB2 amplification status as a covariate." (PMID 38908022, 2024). "Finally, elevated EGFR or ErbB2 levels sensitize cancer cells to ferroptosis-inducing treatment in a mouse xenograft model." (PMID 39604370, 2024). "Consistently, overexpression of ErbB2 enhances cancer cell sensitivity to ferroptosis." (PMID 39604370, 2024). "Therefore, a better understanding of the biology of ERBB2-driven cancer supports the development of new treatment options for patients." (PMID 39067134, 2024). "In addition, we analyzed the expression of ERBB2 in various malignant tumors using data from the Human Protein Atlas." (PMID 37324014, 2023). "We here engrafted the additional specificity to the CD19scFv-CAR T cells by adding a composite protein consisting of the herceptin derived anti-ErbB2 4D5scFv domain for the cancer cell targeting and of the CD19 ectodomain, to allow the engagement by the anti-CD19 CAR." (PMID 36672182, 2023). "ERBB2 has been reported to be amplified or overexpressed in clinical cancers, 15%–30% of mammary, 10%–30% of stomach including gastroesophageal junction and other cancers, such as those of the lung, ovary, bladder." (PMID 36259134, 2023). "In solid tumors, the high essentiality of EGFR and ERBB2 may suggest that these genes are highly important to the viability of cancer cells in their respective solid tumor indications." (PMID 37835579, 2023). "Similarly, most of the genes these variants locate on are associated with one (20.86%) or two (55.83%) indications, with exceptional BRAF, ERBB2, KRAS and EGFR associated with >10 types of cancer indications." (PMID 36856726, 2023). "Genes involved in endocrine resistance pathways primarily fell into 3 functional categories: ERBB2/IGF1R, CCND1, and BCL2, which have been reported to be associated with endocrine resistance and an increased risk of cancer recurrence in breast cancer." (PMID 37328469, 2023). "Thereby, the CD19-CAR T cells gain specificity for the ErbB2+ cancer cells." (PMID 36672182, 2023). "This aligned with the hypothesis that HER2+ cancers arise through HER2 (ERBB2) amplification in cells committed to the luminal lineage." (PMID 37717006, 2023). "The ERBB2 gene, which induces the production of HER2, was selected due to its association with heightened cell proliferation rates and overexpression in SKOV-3 cells and various other cancer cell types." (PMID 37958473, 2023). "Taken together, our data demonstrate that we can control ERBB2 across many cancer types and as well control the major drivers of cancers, which is aneuploidy without causing genome rearrangement." (PMID 37359373, 2023). "Yet, they work across various ERBB2-expressing cancers from diverse biological organs." (PMID 37359373, 2023). "ErbB2 is also expressed by healthy epithelia, although at lower densities than by cancer cells." (PMID 36672182, 2023). "Gene amplification or overexpression of the protein encoded by the erb‐B2 receptor tyrosine kinase 2 (ERBB2) gene, human epidermal growth factor receptor 2 (HER2), is associated with aggressive growth and poor clinical outcomes in a variety of cancers, including breast, ovarian, and gastric." (PMID 37119523, 2023). "Interestingly, cancer cells with higher levels of mtErbB2 were more resistant to the ErbB2-targeting antibody trastuzumab." (PMID 37109525, 2023).
cancer (continued). "We asked whether the CD19-CAR T cells can be efficiently redirected against the ErbB2+ cancer cells while taking advantage of the beneficial properties of the CD19-CAR." (PMID 36672182, 2023). "For patients with ERBB2-positive cancer, the proportion treated with trastuzumab in early-stage cancer in China increased significantly, with an MAPC of 22.1% (95% CI, 17.4%-26.9%; P < .001), and overtook that in the Flatiron database since 2017 (1684 [68.5%] vs 550 [62.5%]; P < .001)." (PMID 37389867, 2023). "As illustrated by the circos plots, DNA‐Seq of the cfDNA samples detected several cancer‐related genomic alterations and confirmed the amplification of ERBB2 (on chromosome 17) of patients PMB 2.8 and PMB 2.36, in line with diagnostic tissue biopsy in situ assessment." (PMID 38046436, 2023). "Could, for example, the constitutive activation of Erbb2/Her2 seen in some carcinomas be mimicking the proliferative wound signal, access of apical Nrg1 ligand to basolateral Erbb2 ?" (PMID 36811403, 2023). "The pattern of co-mutation of cancer-related genes varied among carcinomas and the groups, with group 1 showing a low frequency of co-mutated genes in all carcinomas and groups 2 and 3 showing varying degrees of mutations in MAPK and PI3K/MTOR pathway genes downstream to ERBB2." (PMID 37754252, 2023). "Notably, the ERBB2 mutations in EAC, GC, and CRC were genetically heterogeneous, with substantial diversity in the co-mutation patterns among carcinomas and within groups." (PMID 37754252, 2023). "Here, we report to apply the same CAR to target solid tumors, such as ErbB2+ carcinoma." (PMID 36672182, 2023). "Interestingly, we noticed that when the ERBB2 level is high in cancer compared with the matching normal tissue, the ATM level in cancer shows deregulation compared with ATM levels in normal matched tissue." (PMID 36056635, 2022). "PHLDA1 downregulation was proved to promote acquisition and maintenance of drugs resistance targeting receptor tyrosine kinase, which might suppress the effect of trastuzumab treatment on ERBB2 amplification cancers." (PMID 36010842, 2022). "ERBB2 abnormalities frequently occur and serve as rationale therapeutic targets in cancer." (PMID 35911441, 2022). "We prove that ERBB2 is a direct target of miR-940 based on bioinformatic analysis and luciferase reporter gene experiments, and ERBB2 was considered to be an oncogene active in almost all cancers studied." (PMID 37304410, 2022). "The ErbB oncogenic receptor tyrosine kinase family proteins (ErbB1, ErbB2, ErbB3, and ErbB4) have been shown to contribute significantly to pro-proliferation, migration, invasion, and drug resistance characteristics of diverse cancer cell types." (PMID 35806132, 2022). "The co-expression of ErbB2 and ErbB3 was reported in different types of cancers." (PMID 35177646, 2022). "Since the interactions of ErbB3 with ErbB1 and ErbB2 are critical for oncogenic signaling, it has been anticipated that ErbB1- or ErbB2-overexpressing cancers could be promising targets." (PMID 35806132, 2022). "Abnormal amplification of the ERBB2 proto-oncogene could result in increased tumorigenesis of cancers." (PMID 36172165, 2022). "However, similarly to ErbB2, its clinical significance in the survival of patients with this cancer is contradictory." (PMID 35448172, 2022).